NOTCH3 (notch receptor 3)
Diseases named in the same sentence as NOTCH3 in open-access papers (continued):
Sharing a sentence is not in itself a finding about the gene and the disease.
CADASIL (continued). "This study aimed to evaluate the utility of immunohistochemical staining of vascular Notch3 deposits in biopsied unfixed frozen skin samples from patients with suspected cerebral autosomal dominant arteriopathy with subcortical infarcts and leukoencephalopathy (CADASIL)." (PMID 35775048, 2022). "It is hard to clarify the pathogenicity of variants in Notch3 intracellular domain based on current consensus that accumulation of Notch3 extracellular domain, not intracellular domain, is the pathogenic mechanism of CADASIL." (PMID 34335700, 2021). "However, some patients with NOTCH3 mutations do not show the typical clinical and imaging features of CADASIL." (PMID 32477100, 2020). "However, it has recently been reported that a subset of patients with NOTCH3 gene mutations show atypical clinical symptoms of CADASIL, such as absence of temporal pole lesions, elderly onset, and cerebellar atrophy." (PMID 32477100, 2020). "Cerebral autosomal dominant arteriopathy with subcortical infarcts and leukoencephalopathy (CADASIL), a hereditary cerebral small vessel disease caused by mutations in NOTCH3, is characterized by recurrent stroke without vascular risk factors, mood disturbances, and dementia." (PMID 32457593, 2020). "Aside from the direct effect Notch3 can exert on neurogenesis by its expression in neural precursor cells, the Notch3-dependent vascular influence might, in turn, also be responsible for the observed cognitive impairments in CADASIL patients." (PMID 28345617, 2017). "As this was a cross-sectional analysis of prospectively collected data, it is probable that more severe cases of CADASIL are detected earlier, while there may be many NOTCH3 mutation-carrying individuals with few or no symptoms that remain undiagnosed." (PMID 27309730, 2016). "Herein, we describe a 47-year-old male scholar with a genetically confirmed diagnosis of CADASIL (Arg133Cys mutation in the NOTCH3 gene) and a seemingly negative family history of CADASIL illness, who was investigated with a comprehensive neuropsychological testing battery and neuroimaging methods." (PMID 25009481, 2014). "Prevailing models indicate that cognitive decline might be secondary to vascular pathology, but this remains an open question because the existing mouse knockins of common patient NOTCH3 alleles recapitulate some but not all of the CADASIL pathologies." (PMID 23720232, 2013). "Thus, suggesting that the NOTCH3 rs1044009 polymorphism may be linked to CADASIL or lacunar stroke but not ischemic stroke in general." (PMID 31288479, 2019). "Nonetheless, our findings suggest an LTBP-1-mediated sequestration of LAP into Notch3-ECD aggregates and point to an involvement of the TGF-β pathway in CADASIL pathogenesis." (PMID 25190493, 2014). "Different endocytic ectodomain shedding mechanisms and signal activation pathways may be relevant as a source of the long-term accumulation of the mutant NOTCH3 ECD in VSMCs and for understanding heterogenous pathological outcomes in CADASIL patients." (PMID 40764588, 2025). "Importantly, the review emphasizes that the observed association between CADASIL and large artery disease might not merely be coincidental, especially given the higher prevalence of NOTCH3 mutations among Asian populations, which could predispose them to vascular abnormalities." (PMID 40869930, 2025). "The most widely accepted hypothesis is that the mutant NOTCH3 protein exerts a toxic effect on VSMC membranes, contributing to the pathogenesis of CADASIL." (PMID 40470487, 2025). "Therefore, we investigated whether rare and functional variants in Alzheimer-related genes from the protein analysis through evolutionary relationships (PANTHER) AD-Presenilin pathway were present in patients with suspected CADASIL, but without NOTCH3 mutations." (PMID 36175824, 2022).
CADASIL (continued). "The patient was clinically suspected to have Cerebral Autosomal Dominant Arteriopathy with Subcortical Infarcts and Leukoencephalopathy (CADASIL), but NOTCH3 single gene sequencing (exons 3–6) resulted negative." (PMID 35959404, 2022). "Cerebral autosomal dominant arteriopathy with subcortical infarcts and leukoencephalopathy (CADASIL) is an autosomal dominant, not fully penetrant disorder caused by mutations in the NOTCH3 (Notch Receptor 3) gene." (PMID 35976293, 2022). "Currently, there is none therapeutic treatment available for CADASIL and thereof no drug which can act specifically on the Notch3 protein receptor." (PMID 31218211, 2019). "The neuropathology of CADASIL is characterised by arteriopathy in perforating arteries, subcortical infarcts and deposition of granular osmiophilic material (GOM) in proximity to vascular smooth muscle cells (VSMCs), which contains fragments of the extracellular domain of NOTCH3 (N3ECD)." (PMID 37158955, 2023). "Thus far, there is no clear consensus on the involvement of canonical Notch3 signaling pathway in the pathogenesis of CADASIL, though recent studies seem to support gain of toxic function rather than loss of function." (PMID 32188464, 2020). "Altogether, these data suggest that compromised NOTCH3 function may not be the primary determinant of CADASIL disease, prompting to speculation that CADASIL may be related to a protein gain-of-toxic function rather than loss of function." (PMID 32231578, 2020). "However, little is known regarding the neuroimaging features of CADASIL patients, SVCI with NOTCH3 variants, and SVCI without NOTCH3 variants (genetic and sporadic types), which share similar phenotypes." (PMID 30692550, 2019). "Several NOTCH3 alterations that do not affect cysteine residues have been reported in families with CADASIL, which may involve other disruptions to protein function, though these may result in changes that effectively change cysteine residue availability." (PMID 27881154, 2016).
breast carcinoma (147 papers, 2009 to 2025). "In tumors such as breast cancer, various members of the Notch pathway, including Notch1, Notch3, DLL1, and DLL3, have been implicated in either promoting or inhibiting angiogenesis." (PMID 40486870, 2025). "We recently showed that COMP mediates the Notch3-Jagged1 interaction, enhancing breast cancer stem cells associated with AKT, PI3K, and β-catenin signaling pathways." (PMID 38615020, 2024). "Notch3 expression was very weak in breast cancer cells and was associated with good patient prognosis." (PMID 36854682, 2023). "We also propose a mechanism for Notch3 loss in breast cancers, by demonstrating that Notch3 promoter’s methylation is negatively correlated to its expression." (PMID 36854682, 2023). "Conversely, silencing of Notch3 expression by siNotch3 decreased STAT5A expression, supporting that STAT5A expression is positively associated with Notch3 in human breast cancer cell lines and breast cancer tissues." (PMID 38124049, 2023). "Analysis from the Human Protein Atlas revealed that increased Notch3 protein expression was associated with improved survival in patients with breast cancer (p = 0.050)." (PMID 38124049, 2023). "Here, to unravel the as yet debated role of Notch3 in breast cancer development, we investigated its expression in human breast cancer samples and effects of its loss in mice." (PMID 36854682, 2023). "Meanwhile, the expression abundance of Notch3 and GSK3β was associated with different breast cancer subtypes, and significantly increased in luminal breast cancer type compared with other subtypes (p = 0.037)." (PMID 36139447, 2022). "Notch3 is also implicated in inhibiting cell proliferation and invasion in breast cancer through PTEN transactivation." (PMID 35884426, 2022). "The risk score of breast cancer patients was calculated using the following formula: Risk score = −0.482 * expression of CPEB1 + 0.468 * expression of NOTCH3 + 0.213 * expression of NUAK1 + 0.321 * expression of PDPK1." (PMID 36072578, 2022). "To further investigate the association of Notch3 and GSK3β in breast cancer, we evaluated the protein and mRNA expression levels of GSK3β in MCF-7 and MDA-MB-231 cell lines with high and low expression of Notch3." (PMID 36139447, 2022). "Accumulating evidence demonstrated that Notch3 and ER were highly correlated in different subtypes of breast cancer, which was associated with a better prognosis." (PMID 34006834, 2021). "In ER+ primary breast cancer, NOTCH3 expression was associated with prolonged relapse-free survival." (PMID 32210163, 2020). "Given that Notch4 and Notch3 are expressed at higher levels in poorly differentiated basal breast cancers it will be important to elucidate the association of different Notch pathways with Tregs during cancer formation." (PMID 30061899, 2018). "Notch4 and Notch3 are expressed at higher levels in poorly differentiated basal breast cancers and are associated with poor overall survival." (PMID 30061899, 2018). "Notch3 expression either in nuclear or in cytoplama was strongly associated with that of GATA-3 in breast cancer tissue samples (Pearson r = 0.408, P = 0.001)." (PMID 30100605, 2018). "Increased expression of NOTCH1 and NOTCH3 has been particularly associated with aggressive basal breast cancer." (PMID 30388742, 2018). "In this study, we demonstrated that NOTCH3 expression is linked to cancer cell seeding and development of breast cancer metastases." (PMID 30180881, 2018). "These microvesicles were capable of blocking endocrine therapy Notch3 down regulation and causing an estrogen-independent phenotype in breast cancer cells." (PMID 30515368, 2018). "Our findings unequivocally demonstrate that Notch3 can act as a tumor suppressor in breast cancer epithelial cells, and that loss of Notch3 is an important feature of TNBC." (PMID 27841855, 2016).
breast carcinoma (continued). "In human breast cancer samples, Notch3 expression is positively associated with GSK3β (r = 0.416, p = 0.001); moreover, high expressions of Notch3 and GSK3β mRNA are correlated to better relapse-free survival in all breast cancer patients via analysis in “the Kaplan–Meier plotter” database." (PMID 36139447, 2022). "Future experiments will verify whether Notch3 can activate PTEN in PTEN-deficient breast cancer cell lines." (PMID 34006834, 2021). "In close to 10,000 breast cancer samples (using default settings to avoid multiple testing, thus including a heterogeneous cohort of all breast cancer patients available), notch-1 and notch-3 expression was positively associated with MSI-1." (PMID 34291358, 2021). "Dysregulated NOTCH3 expression has often been linked to a more aggressive disease, and in triple-negative breast cancer reported as an oncogene, while in luminal breast cancer, NOTCH3 upregulation has been associated with increased relapse-free survival." (PMID 33775697, 2021). "Additionally, evidence from nonsense and missense mutations in multiple cancers, including breast cancer, showed tumor suppressor capabilities of Notch3 through controlling of the cellular senescence pathway." (PMID 30515368, 2018). "On the basis of these results, we developed unique NOTCH3-knockout breast cancer cells (vMCF-7Raf-1 1GXCRISPR-NOTCH3) to abrogate NOTCH3 expression and evaluate the causative role of NOTCH3 signaling in promoting stemness and invasive properties of vMCF-7∆Raf1 1GX cells." (PMID 30180881, 2018). "Our analysis showed that aberrant NOTCH3 expression was significantly associated with decreased overall patient survival, supporting the pivotal role of NOTCH3 oncogenic pathway in promoting breast cancer progression." (PMID 30180881, 2018). "Both ATRA and IIF down-regulated genes that supported the tumour stem cell phenotype maintenance (Slug, Notch-3 and Jagged-1) by blocking the NF-κB axis: these events were associated with re-expression of differentiation markers such as ERα and keratin-18 in breast carcinoma stem cells." (PMID 28465354, 2017). "Conversely, loss of a Notch negative regulator, Numb, is found to be associated with higher grade and worse prognosis in primary breast cancer, and suppression of Notch activity by Notch3 and CSL knockdown promotes cancer cell apoptosis and inhibits tumor cell growth." (PMID 25309874, 2014). "In addition, Notch3 and GSK3β expression was positively associated in human breast cancer samples." (PMID 36139447, 2022). "Furthermore, these data also indicate that Notch3 expression may be positively associated with that of E-cadherin in breast cancer." (PMID 27841855, 2016). "Two cell types were used, MCF7 which is a breast cancer cell line that expresses NOTCH3, and VSMCs differentiated from hESCs." (PMID 40764588, 2025). "In contrast, DEGs associated with inhibiting breast cancer metastasis (HTRA3 and NOTCH3) were negatively correlated with 23 metabolites and positively correlated with 39 metabolites." (PMID 41179294, 2025). "In another study, JAG1-positive fibroblasts were shown to interact with Notch3 in breast cancer cells to regulate resistance to chemotherapy." (PMID 39951484, 2025). "For example, AuNPs functionalized with PEG and loaded with miR-206 mimics have been shown to arrest breast cancer cells in the G0-G1 phase by targeting the NOTCH3 (notch receptor 3) gene." (PMID 40260417, 2025). "Specifically, we observed up-regulation of genes that drive breast cancer metastasis (IL13RA2, MMP3, PTGS1, SYK, VCAN, and FLT1) and downregulation of metastasis-associated suppressor genes (NOTCH3, and HTRA3)." (PMID 41179294, 2025). "In breast cancer, Notch1 enhances cancer cell proliferation and sustains cancer stem cell activity, whereas Notch3 suppresses epithelial-mesenchymal transition (EMT) by activating glycogen synthase kinase 3 beta (GSK3β) expression." (PMID 41050674, 2025).
breast carcinoma (continued). "miR-9 enhances Notch signaling in breast cancer by targeting and upregulating Notch3, which drives breast cancer progression." (PMID 40621472, 2025). "PF-06650808, a novel anti-NOTCH3 ADCs, exhibited a promising antitumor activity in a clinical study of breast cancer (NCT02129205)." (PMID 39557868, 2024). "These regions encompassed 242 genes, including some ones previously related with oncogene activity in TNBC breast cancer like NOTCH3 and PKN1." (PMID 39239354, 2024). "NOTCH3 is down-regulated in TGF-β-induced breast cancer cell MCF-7, consistent with previous reports." (PMID 38164285, 2024). "Previously, we showed that COMP secreted by breast cancer cells promotes the CSC population by activating the Notch3 signaling pathway." (PMID 38615020, 2024). "In patients with breast cancer, the level of NOTCH3/miR-223/ZEB1 was analyzed and their prognostic value determined." (PMID 38164285, 2024). "A low level of NOTCH3 or high level of ZEB1 was correlated with poor overall survival (OS) of patients with breast cancer, with HR = 0.88, p = 0.0095 and HR = 3.93, p = 0.023, respectively." (PMID 38164285, 2024). "Our preliminary results showed the opposite expression pattern of NOTCH3 and ZEB1 in breast cancer, which predicts a potential regulatory axis between NOTCH3 and ZEB1." (PMID 38164285, 2024). "In reporter gene assays, NOTCH3 directly binds to the promoter element of miR-223 in breast cancer cells, which indicates that NOTCH3 directly promotes the expression of miR-223." (PMID 38164285, 2024). "Consistently, for breast cancer patients, higher expression of NOTCH3 was positively correlated with metastasis-free survival (MFS) (p = 0.0011, HR = 0.519), whereas the expression level of ZEB1 was negatively correlated with MFS (p = 0.00413, HR = 2.43)." (PMID 38164285, 2024). "NOTCH3 inhibited the proliferation and invasion of breast cancer cells via up-regulating the expression of miR-223." (PMID 38164285, 2024). "In line with this, a recent study demonstrated that Notch3 signaling promotes PD-L1 overexpression in breast cancer cells, and specific Notch3 silencing results in PD-L1 downregulation, providing a novel strategy for anti-PD-L1 combination therapies." (PMID 39766289, 2024). "In the GSE26304 dataset 35, NOTCH3 expression was positively correlated with OS (p = 0.0231, HR = 0.274), whereas ZEB1 expression was negatively associated with OS of breast cancer patients (p = 0.00365, HR = 6.43)." (PMID 38164285, 2024). "Exosome transfer from stromal cells to breast cancer cells has been identified, with RNA within these exosomes modulated radioresistance within the breast cancer cells by regulating the STAT1/NOTCH3 pathway." (PMID 39540151, 2024). "The results showed that high expression of miR-223 and NOTCH3 are related to good prognosis of breast cancer patients." (PMID 38164285, 2024). "This NOTCH3-mediated pathway inhibits the proliferation and malignancy in breast cancer, suggesting a role for NOTCH3 in delaying cancer progression in dysplastic lesions of the larynx." (PMID 39273632, 2024). "Breast cancer patients with high expression of NOTCH3 tended to have long DRFS (p = 0.236, HR = 0.583), while high ZEB1 levels predicted poor DRFS in patients with breast cancer (p = 0.0151, HR = 2.59)." (PMID 38164285, 2024). "NOTCH3 is very weakly expressed in breast cancer cells, which prevents tumor occurrence through HeyL-mediated inhibition of Mybl2 (an important cell cycle regulator), and is related to good prognosis." (PMID 38164285, 2024). "In a phase I trial (NCT02129205), 40 patients with advanced breast cancer (BC) and other solid tumors unselected for Notch3 expression were studied for safety, pharmacokinetics, immunogenicity, and early anticancer efficacy of single-agent PF-06650808." (PMID 39456611, 2024).